GATAD2B (GATA zinc finger domain containing 2B)
Diseases named in the same sentence as GATAD2B in open-access papers (continued):
Sharing a sentence is not in itself a finding about the gene and the disease.
cancer (4 papers, 2018 to 2025). A tumor composed of atypical neoplastic, often pleomorphic cells that invade other tissues. "A number of components of the NuRD complex have been linked to cancer, including GATAD2B, a key scaffold-protein in the complex." (PMID 40136647, 2025). "Overexpression of GATAD2B also significantly increased the expression of cancer stem-like markers at both protein and mRNA level." (PMID 40136647, 2025). "WT or Mut GATAD2B were stably overexpressed in cells and cancer stem-like cells properties were analyzed." (PMID 40136647, 2025). "Consistent with RNAi results, infection with GATAD2B gRNA reduced GATAD2B levels and levels of cancer stem-like cells markers SOX2 and c-Myc, and significantly reduced mammosphere formation when compared to control gRNA." (PMID 40136647, 2025). "We further validated the interaction of NOTCH1 with histone deacetylase 1 or GATAD2B using protein network analysis, proximity-based ligation, in vivo cross-linking and coimmunoprecipitation assays in several Notch-addicted cancer cell lines." (PMID 38043798, 2024). "Similarly, the population of cancer cells undergoing apoptosis with GATAD2B overexpression was significantly reduced compared to control cells." (PMID 40136647, 2025). "Additionally, overexpression of GATAD2B also significantly increased the population of cancer stem-like cells detected by ALDEFLOUR staining in MDA-MB-231 cells and SUM159 cells or by SORE-GFP reporter assay compared to controls." (PMID 40136647, 2025). "Since GATAD2B depletion attenuated CSC potential, we examined whether GATAD2B was sufficient to promote cancer stem-like cells phenotypes." (PMID 40136647, 2025). "Since the number of mammospheres reflects the abundance of cancer stem-like cells, we tested whether reducing GATAD2B levels alters the cancer stem-like cell population." (PMID 40136647, 2025). "However, the specific role of GATAD2B in cancers is poorly investigated." (PMID 39696035, 2024). "Reduced expression of GATAD2B in MDA-MB-231, SUM159, and HCI-10 cell lines resulted in a significant decrease in the population of ALDH+ cancer stem-like cells compared to control cells." (PMID 40136647, 2025). "Our data suggest that HDAC1 and some other identified interacting proteins such as GATAD2B in this study may be essential partners for NOTCH1 function and may serve as important therapeutic targets in NOTCH1-dependent cancers." (PMID 38043798, 2024). "Importantly, re-expression of WT GATAD2B, but not GATAD2B-Mut, rescued expression of cancer stem-like cells markers, as well as mammosphere formation in MDA-MB-231 and HCI-10 cells." (PMID 40136647, 2025).
neurodevelopmental disorder (3 papers, 2021 to 2025). A behavioral and cognitive disorder with onset during the developmental period that involves impaired or aberrant development of intellectual, motor, or social functions. "Thus, we have uncovered genes involved in proliferation, migration and differentiation, many of which are involved in neurodevelopmental disorders, as being associated with Gatad2b expression." (PMID 38238293, 2024). "Variants in ASD-associated genes (CHD8, FOXP1, and SHANK1) and genes linked to other neurodevelopmental disorders (CDH15, GATAD2B, and SHROOM4) were also detected." (PMID 40642607, 2025).
tumor (2 papers, 2018 to 2024). "Isolation of genomic DNA from primary tumor followed by barcode sequencing revealed robust enrichment of GATAD2B-associated barcode as expected for SQ tumor site and metastasis-infiltrated tissues originating from GATAD2B-transduced HBEC-iKRASG12D cells." (PMID 30013058, 2018). "Consistent with the ability of GATAD2B to drive in vivo metastasis of 393 P cells in our primary screen, necropsies of tumor-bearing HBEC-iKRASG12D-GATAD2B mice revealed distant metastases (N = 4/5 mice examined) to multiple lymph nodes and other organ sites." (PMID 30013058, 2018). "Animal necropsies confirmed marked tumor burden in GATAD2B-Cre infected mice, which was consistent with Luciferase imaging." (PMID 30013058, 2018). "Together, these data indicate that GATAD2B physically associates with MYC and that MYC is required for GATAD2B-dependent tumor growth in KRASG12D-expressing cells." (PMID 30013058, 2018). "We demonstrate that GATAD2B enhances tumor growth, at least in part, through a direct interaction with MYC, a known potent oncogenic and metastasis driver that also scored in the in vivo screen." (PMID 30013058, 2018). "One paper identified GATAD2B to enhance tumor growth through direct interaction with MYC." (PMID 39696035, 2024). "We next examined whether GATAD2B expression would influence HBEC-iKRASG12D tumor growth and/or metastasis when subcutaneously implanted into the flanks of athymic mice." (PMID 30013058, 2018). "Taken overall, these in vivo data demonstrate that KRASG12D expression is necessary for tumor formation, but insufficient to support progressive tumor growth, while combined expression with GATAD2B drives progressive tumor growth that is dependent on continued KRASG12D signaling." (PMID 30013058, 2018). "Given that KRAS and MYC are currently therapeutically undruggable genetic alterations found in many tumor types, a greater understanding of the interaction and cooperativity between these oncogenic changes and GATAD2B may open up the exploration of new therapeutic approaches." (PMID 30013058, 2018).
neurological disorders (1 paper, 2025). "Dysregulation of GATAD2B was reported in multiple neurological disorders, which is potentially linked to the role of GATAD2B and NuRD complex in regulating function of stem cells and progenitor cells." (PMID 40136647, 2025).
GATAD2B also shares sentences with these, for which no sentence is quoted: adenocarcinoma (1 paper); apraxia (1); bipolar disorder (1); brain malformations (1); CHARGE syndrome (1); infection (1); language disorder (1); mood disorder (1); schizophrenia (1); squamous cell carcinoma (1); X-linked mental retardation syndrome (1).